AKT3 (AKT serine/threonine kinase 3)
Diseases named in the same sentence as AKT3 in open-access papers (continued):
Sharing a sentence is not in itself a finding about the gene and the disease.
cancer (continued). "More prevalent amplification of the oncogene AKT3 has been detected in many cancers, such as breast carcinoma, endometrial carcinoma, melanoma, ovarian epithelial tumor, cholangiocarcinoma, and non-small cell lung cancer." (PMID 35402264, 2022). "This warrants a detailed assessment of the role of AKT2 and AKT3 targeting by lncRNAs in regulating cancer cell functions in the future." (PMID 36230902, 2022). "Although many circRNAs were shown to target AKT1, AKT2, and AKT3, only some were capable of modulating cell functions (apoptosis and migration) in cancer cells based on the literature search." (PMID 36230902, 2022). "Protein kinase B and its three paralogs, akt1, akt2, and akt3, exhibit intensively deliberated cancer and metabolism, and also regulate the plasma membrane and cell size mutations in Drosophila." (PMID 36362447, 2022). "AKT3 increases migration and metastasis in cancer cells, while a knockdown of this gene induces mitochondrial dysfunction." (PMID 33596996, 2021). "Taken together, these results highlight that AKT3 is a kinase that is highly expressed in the stromal compartment as well as in cancer cells that belong to CMS4, both in preclinical models and patient samples." (PMID 33673003, 2021). "We found that protein AKT3 is highly expressed in CMS4, and that active AKT3 inhibits a protein that stalls growth of cancer cells (p27KIP1)." (PMID 33673003, 2021). "Subsequently, the consequences of an increased AKT3 protein level in NE-like cancer cells were analyzed." (PMID 33540707, 2021). "AKT, is a serine/threonine protein kinase comprising three isoforms—namely: AKT1, AKT2 and AKT3, whose inhibitors have been recognized as promising therapeutic targets for various human disorders, especially cancer." (PMID 33920446, 2021). "Our in vitro data as well as that of others indicate that growth of mesenchymal cancer cell lines can be diminished as long as AKT3 is also targeted." (PMID 33673003, 2021). "Since AKT is recognized as playing a vital role in cancer progression, AKT3 inhibition has a therapeutic potential by inhibiting both cancer cells and CAFs." (PMID 33799788, 2021). "AKT3 expression was similarly increased in cancers with AKT3 amplification, but with a much lower significance (28%; p = 0.036)." (PMID 33921698, 2021). "In conclusion, AKT3 is a potential target for cancer therapy that inhibits the pro-tumoral function of CAFs and reverses CAF-mediated immunosuppression." (PMID 33799788, 2021). "It has three different subtypes, AKT1, AKT2, and AKT3, which are closely related to the development of human cancer." (PMID 34956562, 2021). "We found AKT3 to be expressed in the cancer cell epithelium of CRC specimens, patient derived xenograft (PDX) models and in (primary) cell cultures representing CMS4." (PMID 33673003, 2021). "Amongst the cancer-relevant microRNAs, miR-582-5p suppresses cell growth and tumorigenesis by inhibiting the expression of oncogenes, including AKT3, MAP3K2 and NOTCH1." (PMID 33670427, 2021). "We can target AKT3 with inhibitors which leads to strongly reduced growth of cancer cell lines that are categorised as CMS4." (PMID 33673003, 2021). "When cell lines derived from different carcinomas that all heterogeneously express AKT3 were analysed, high AKT3 expression was very strongly associated with EMT gene set enrichment." (PMID 33673003, 2021). "MiR-29b, which we had shown is induced by pcDNA3.1-lnc-EPC1-4 and inhibited by lnc-EPC1-4 siRNA, has also been suggested to participate in the inhibition of angiogenesis and tumorigenesis of cancer through the Akt3 signaling pathway." (PMID 32554864, 2020). "hsa-miR-5585-3p_L-3R-1_1ss5AG and hsa-mir-7851-p5_1ss12AC targeting AKT serine/threonine kinase 3 (AKT3) played swinging roles in the tumorigenesis, development, and progression of various types of cancer, including CRC." (PMID 32293320, 2020).
cancer (continued). "On the contrary, longer cancer-specific survival was recorded in luminal A BC patients with higher expression levels of AKT3." (PMID 31781306, 2019). "A better cancer-specific survival was found for higher levels of AKT3 in luminal A BC patients (p = 0.0009)." (PMID 31781306, 2019). "During investigations of the AKT signaling more and more evidence raised that the three isoforms AKT1 (PKBα), AKT2 (PKBβ) and AKT3 (PKBγ) exert distinct and partly even opposing effects in cancer and physiologically." (PMID 31752925, 2019). "Our study indicates that n384546 exerts its oncogenic properties in PTC tumorigenesis by sponging miR-145-5p and then regulating its target AKT3, which has been proven to be an oncogene in several cancers." (PMID 31160577, 2019). "Targeting to CDCA4, BCL2L2, YAP1, AKT-3 and Cyclin E1, miR-15a has been found to significantly reduce cancer cell survival and aggressiveness." (PMID 30733644, 2019). "The expression and activation of AKT3 mediates cancer progression and controls cellular processes such as cell growth, proliferation, apoptosis, and invasion." (PMID 31703725, 2019). "AKT3 has been reported to be involved in cancer progression and function as an oncogene in many types of cancers by regulating the PIK3/AKT signal pathway." (PMID 30186040, 2018). "Triciribine’s target of inhibition Akt, also known as protein kinase B (PKB), is a serine/threonine kinase that has three isolated isoforms: Akt1 (PKBα), Akt2 (PKBβ) and Akt3 (PKBγ), whereby Akt1 is specifically up-regulated in most cancers." (PMID 30323898, 2018). "Total AKT (Akt1, Akt2 and Akt3) increased during development of various cancers, but in contrast, Akt1 levels were seen to be diminished." (PMID 28659381, 2017). "It was reported that in several human cancer cell lines, Akt1 localizes in cytoplasm and Akt2 colocalizes with mitochondria, while Akt3 localizes in both nuclear membrane and nucleus." (PMID 28483982, 2017). "Among these, the mRNA levels of PIK3R1 and CTNNB1 were increased more than 2-fold, and those of PIK3R3, PIK3CA and AKT3 were increased 1.6- to 1.9-fold after co-culture with cancer cells." (PMID 28173828, 2017). "Further analyses of 407 carcinomas in the TCGA data set revealed that tumors expressing high levels of FGF-2 tend to also express high levels of Akt3." (PMID 28515962, 2017). "We selected 6 genes (MUC4, MUC13, MUC20, BMP7, AKT3, and SMAD3) that were closely associated with the development and progression of cancer to validate the conclusions drawn from the gene expression profiling analysis." (PMID 26673820, 2016). "The mutation of all three isoforms of Akt, AKT1/PKBα, AKT2/PKBβ and AKT3/PKBγ are also observed in multiple types of cancers." (PMID 25334061, 2014). "Akt3 has been studied extensively in cancer cells for its effects on cancer development, proliferation and migration;25,26 however, little is known regarding its function in normal cells." (PMID 25275594, 2014). "There are three AKT isoforms (AKT1, AKT2, and AKT3) with different expression patterns and functions in several cancer tumors." (PMID 24338765, 2014). "AKT3 was up-regulated in the Epstein-Barr virus infected cancers progression, such as the proliferation of malignant cells or lymphocytes and immune escape, which might be triggered by EBV-encoded proteins LMP1 and LMP2 in the NPC17." (PMID 40057671, 2025). "We could detect upregulated genes as well (PLAU, SERPINA1, and AKT3), mainly connected to cancer development and progression and mesenchymal phenotypes, that were also responsive to EZH2 inhibition." (PMID 38672463, 2024). "Interestingly, we discovered that the stable expression of EGFP-K-Ras(V12) resulted in reduced PI3-K p85α as well as Akt1 and Akt2 expression, but increased Akt3 expression in PANC-1 as well as Colo-699 cancer cells." (PMID 38291468, 2024).
cancer (continued). "Interestingly, both AKT3 and CDKN1B are linked to clinical head size syndromes and cancer risk and contain, respectively, 3′-UTR variants and an exonic variant that reach genome-wide significance." (PMID 38703765, 2024). "Analyzing miRNA reprogrammed AKT3 profiles and AKT3 regulated miRNA profiles to explore cancer pathogenesis in a personalized or cancer-specific manner may advance the development of effective new therapeutic strategies in the future." (PMID 37998329, 2023). "Knowledge regarding the roles of the dysregulated miRNA/AKT3 axis in oncogenic signaling pathways could be advanced to enable the diagnosis of specific cancer types." (PMID 37998329, 2023). "Circ_0000144 shows cancer-promoting effects on TC cells by regulating the miR-217/AKT3 pathway." (PMID 37998329, 2023). "Alternatively, AKT3 can be regulated by modifying the ncRNA expression for cancer therapy." (PMID 37998329, 2023). "The findings regarding miRNA/AKT3 regulatory networks may revolutionize views regarding the genesis, progression, and treatment of cancer." (PMID 37998329, 2023). "Genetic alterations of the PIK3CA, mTOR, PTEN, AKT1, AKT2, and AKT3 genes in human cancers." (PMID 35402264, 2022). "Several kinds of AKT1-, AKT2-, and AKT3-regulating circRNAs are overexpressed in many cancer cells." (PMID 36230902, 2022). "Furthermore, Akt3 is regulated at the transcriptional level.A present study reported the influence of miR-145-3p on cancer autophagy." (PMID 35369850, 2022). "The expression of miR-22-3p inactivated AKT3 to inhibit the proliferation of cancer cell." (PMID 35615247, 2022). "AKT3 is abnormally expressed in various cancers and affects cancer progression." (PMID 36593867, 2022). "Indeed, we recently identified Slug as a downstream target of YB1 in Akt3-mediated cancer stemness in TNBC." (PMID 36291790, 2022). "This suggests that AKT3 contributes to the growth of mesenchymal/CMS4 cancer cells and that selective inhibition of this kinase could represent a novel therapeutic avenue to decrease growth of this subtype." (PMID 33673003, 2021). "Overall, our findings suggested that the suppression of spermatogonial proliferation by apigenin treatment was mediated by the downregulated Prmt7/Akt3 pathway and the concentration should be taken into account in future applications of apigenin for cancer therapy in men." (PMID 34830091, 2021). "Furthermore, AKT3 is a potential target for cancer therapy that inhibits the pro-tumoral function of CAFs." (PMID 33799788, 2021). "Overall, our study supports that apigenin can interfere with mouse spermatogonial proliferation by way of the downregulated Prmt7/Akt3 pathway, which demonstrates that the concentration should be taken into account in future applications of apigenin for cancer therapy of men." (PMID 34830091, 2021). "Furthermore, overexpression of Akt3, both the main and splice isoforms, drove cancer cell apoptosis." (PMID 34591413, 2021). "Akt3 is also required for mitochondrial function in cancer cells." (PMID 33087445, 2020). "Some studies found that AKT3 was up-regulated in many types of cancers and knockdown of AKT3 isoforms could abrogate the growth of tumors through inducing cell apoptosis and inhibiting proliferation." (PMID 31703725, 2019). "However, it has three isoforms (Akt1, Akt2, and Akt3) and they perform distinct functions and even play contrasting roles in different cancers." (PMID 31252679, 2019). "However, it is well-known that Akt kinase exists in three different isoforms as Akt1, Akt2, and Akt3, and these display distinct functions in various cancers." (PMID 31252679, 2019). "Several cancer and developmental studies have suggested a role for Akt3 in cellular migration, and demonstrated that the downregulation of Akt3 increases migration and metastasis, and MAP-2+ neurons in neurospheres expressing Akt3 with a specific mutation at E17K, have a defect in migration." (PMID 31404142, 2019).
cancer (continued). "Furthermore, H19 regulated many other cancer-related genes in this network, such as AKT3, CSF1, MET, COL1A1, COL5A1, WWTR1, EPHB4, and TMPRSS3." (PMID 31164794, 2019). "However, AKT3 is also emerging as a critical driver and therapeutic target in a subset of cancer lineages." (PMID 30012111, 2018). "Our findings were consistent with known roles of RIZ1 and Akt3 in cancer pathogenesis." (PMID 29367689, 2018). "In Akt3-knockdown cells, mitochondrial oxygen consumption rate was significantly reduced, indicating a critical role of Akt3 in mitochondrial respiration in human cancer cells." (PMID 29367689, 2018). "With increasing interest in a role for AKT3 in cancer, there may be a future role for AKT3 targeted therapies, which we hypothesize may be useful in the setting of PI3K-mTOR inhibitor resistance." (PMID 29374181, 2018). "Akt1 among other subtypes of Akt (Akt2 and Akt3) is involved in various cancers." (PMID 29088809, 2017). "PDGFRA is connected to AKT3 activity and regulations in participates in cancer related mechanisms." (PMID 29321820, 2017). "However, the molecular mechanisms and effectors downstream of AKT3 in the regulation of cancer cell migration and metastasis remain to be elucidated." (PMID 26741489, 2016). "Therefore, inhibition of Akt3 is a therapeutic strategy for cancers by inducing apoptotic cell death and reversing drug resistance." (PMID 22051041, 2011). "Therefore, a better understanding of regulatory miRNA/AKT3 networks may reveal novel biomarkers for the diagnosis of patients with cancer and may provide invaluable information for developing more effective therapeutic strategies." (PMID 37998329, 2023). "However, studies have also identified the same disrupted miRNA/AKT3 axis in different cancer types." (PMID 37998329, 2023). "Moreover, AKT3-derived circRNAs target some miRNAs in certain types of cancers, thus suggesting that AKT3 might regulate epigenetic modifiers in a post-transcriptional manner." (PMID 37998329, 2023). "However, the level of Akt3 and Stat3 between WT and Pdia4–/– cancer stroma was slightly different." (PMID 35170261, 2022). "Thus, we may conclude that sevoflurane exposure during surgery may contribute to cancer recurrence via AKT3 induced EMT and by all three AKT isoforms enhanced cancer cell survival and proliferation." (PMID 34199634, 2021). "Furthermore, high AKT3 expression in CRC cell lines is associated with enriched expression of EMT marker genes, and this strong association can be expanded to a diverse array of carcinoma cell lines." (PMID 33673003, 2021). "Moreover, lots of evidence suggested that AKT3 was regulated by miRNAs, such as miR-497, miR-338, and miR-16, which could suppress cancer progression." (PMID 31703725, 2019). "However, analogous activating mutations in AKT2 or AKT3 have not been identified in any cancer lineage." (PMID 18813315, 2008). "Inhibitors of AKT3 or FGFR2, which are Enzastaurin or Erdafitinib, have been widely applied in the treatment of several types of cancer as targeted therapies." (PMID 40057671, 2025). "Among the three downregulated genes, AKT3, which is a serine/throne kinase from the AKT family, is involved in the biogenesis of many different types of cancers." (PMID 38491196, 2024). "This sponging leads to the subsequent upregulation of BMI1, KRAS, AKT3, KLF12, and NAMPT, along with several other cancer-promoting genes, thus promoting a more aggressive phenotype." (PMID 39039064, 2024). "Thus, regulating ncRNAs in the miRNA/AKT3 axis to control cancer may be a therapeutic option." (PMID 37998329, 2023). "The Cancer Proteome Atlas (TCPA) created a Kaplan Meier (KM) plot for miR-520c-3p targets AKT1, AKT2, AKT3, MTOR, NF-κB (RelA), PDK1, PI3K, and PTEN." (PMID 35634241, 2022).
cancer (continued). "In the current study, we demonstrated for the first time the promotive role of AKT3 expression in the proliferation and colony formation of NSE cells, indicative of the potential cancer-promoting role of AKT3 in TGCT, especially NSE." (PMID 34882061, 2021). "We focused on AKT3 for further analysis, because PI3K-AKT signaling is attracting attention as one of the most hyperactivated signaling pathways in many types of cancers." (PMID 33799788, 2021). "It has been reported that AKT3 is aberrantly expressed in indifferent type of cancers, such as NSCLC, indicating the importance of AKT3 in regulating NSCLC development." (PMID 34313353, 2021). "Compared to amplifications of MRCKα and AKT3, amplifications of ARID4B showed the strongest enrichment in the Basal cancer subtype." (PMID 33921698, 2021). "Capivasertib was previously shown to inhibit all three isoforms of AKT (AKT1, AKT2 and AKT3) in enzyme assays and reduce phosphorylation of its downstream substrates P70S6K or PRAS40 and in vitro growth of a subset of various cancer cell lines and xenografts." (PMID 34066040, 2021). "Furthermore, high AKT3 expression was associated with high expression of epithelial-mesenchymal transition (EMT) genes, and this observation could be expanded to cell lines representing other carcinoma types." (PMID 33673003, 2021). "We also observed upregulated ALDH activity, which is a CSC marker in different cancers including pancreatic, as well as increased autophagy especially for cancer cells adapted to AKT1 and AKT3 silencing." (PMID 32764385, 2020). "AKT3, KIT proto-oncogene, receptor tyrosine kinase (KIT) and retinoic acid receptor beta (RARB) were also involved in pathways in cancer." (PMID 33176720, 2020). "The miR-221-3p targets genes at early stage such as Annexin A1 (ANXA1), Cyclin Dependent Kinase Inhibitor 1B (CDKN1B), and multiple genes during advance-stage cancer such as CDKN1B, PTEN, Ring Finger Protein 20 (RNF20), Estrogen Receptor 1 (ESR1) and AKT3." (PMID 31756185, 2019). "The well-documented cancer-related genes NOTCH1, CDKN1A, EGR1, AKT3, TNF, MMP9, and SMARCA4 are located in the center of this newly constructed subnetwork." (PMID 28500316, 2017). "Meanwhile, MAPK1, AKT3 and IGF1R regulated by hsa-miR-4429 also participate in the Proteoglycans in cancer (FDR = 0.004268857), Rap1 signaling pathway (FDR = 0.018406673) and Ras signaling pathway (FDR = 0.024181237)." (PMID 26879603, 2016). "CDKN2A has length as the dominant determinant over amplitude in 6/8 cancers, while all 16 cancer types with MYC, CCND2, TERT, or AKT3 amplifications show low AUCs for both parameters." (PMID 26787600, 2016). "Among the three highly homologous AKT isoforms(AKT1, AKT2, and AKT3), most studies have focused on the role of AKT1 in cancer progression." (PMID 26512921, 2015). "EDG3 is necessary for the stimulation of the serine threonine kinase, Akt3, by the vascular endothelial growth factor (VEGF), and reduced levels of Akt kinase leads to increased apoptosis of cancer cells." (PMID 25896894, 2015). "Four of these genes, AKT2, AKT3, G6PC, and GYS1, were particularly interesting because their involvement in the regulation of glycolysis in cancer has been well documented." (PMID 26512921, 2015). "It is noteworthy that many genes within these pathways (e.g., AKT2, AKT3, CREBBP, MAPK1, GNAS, RPTOR) are already known to play relevant roles in cancer cell growth and proliferation, which could provide a plausible biological basis for such a link." (PMID 41226303, 2025). "Additionally, the general pathways in cancer involve 13 genes (FDR of 2.49 × 10−5), including oncogenes and signalling molecules like PKAc, AKT3, and BCL2, which play essential roles in cellular growth and survival mechanisms." (PMID 40699738, 2025).